CCND1 (cyclin D1)
Diseases named in the same sentence as CCND1 in open-access papers (continued):
Sharing a sentence is not in itself a finding about the gene and the disease.
melanoma (continued). "It has been reported that in a subset of melanomas (<8%), the CCND1 gene is amplified, leading to an overproduction of cyclin D1, which enables an aberrant proliferation, diminishing the effectiveness of treatment, and generating a therapy resistance mechanism." (PMID 40872623, 2025). "Melanoma cells exhibit a high proliferative capacity mainly because of the constitutive activation of the ERK and AKT pathways, which results in rapid cell growth through the upregulation of cyclin D1 and cyclin E." (PMID 38339136, 2024). "In melanomas this probe set panel identified interchromsomal rearrangement in chromosome 6 with gains in 6p25 (RREB1) and loses in 6q23 (MYB), as well as common gains in 11q13 (CCND1)." (PMID 39741925, 2024). "Hence, the adaptation of a five-probe FISH assay targeting against 9p21 (CDKN2A), 11q13 (CCND1), and 8q24 (MYC) has improved the discriminatory power for spitzoid melanomas." (PMID 38247727, 2024). "Moreover, bioinformatics analysis confirmed the interactions between the kynurenine pathway, cyclin D1, and CDK4 in melanoma." (PMID 37245164, 2023). "Therefore, we determined the expression of CCND1 and CDKN1A mRNAs in melanoma cells treated with 20, 40, and 60 μM." (PMID 36674631, 2023). "Surprisingly, pterostilbene did not significantly affect CCND1 transcriptional activity in A2058 melanotic melanoma cells; therefore, more studies are required to determine the antiproliferative mechanism of pterostilbene against these cells." (PMID 36674631, 2023). "Similarly, analysis of the melanoma TCGA dataset revealed that GREB1 gene expression was positively correlated with the expression of proliferative marker genes (CDK2, MYC, CCND1, and LIG1) and negatively correlated with CDKN1B." (PMID 37658191, 2023). "Consistently, expression/nuclear accumulation of nonphosphorylatable cyclin D1 (T286A) in melanoma cells strongly interferes with S phase NER and enhances cytotoxicity post-UV." (PMID 37301510, 2023). "Indeed, we observed that miR-195-5p expression level is negatively correlated with both genes in melanoma patients, reinforcing the finding that miR-195-5p/CCND1 and miR-195-5p/YAP1 axis are involved in human melanoma progression." (PMID 37174717, 2023). "We subsequently stratified the MSKCC IO-cohort based on the percentile of TMB, and the result showed that patients with melanoma harboring CCND1 amplification did not benefit from ICIs regardless of TMB status." (PMID 35844619, 2022). "Activation of canonical WNT signaling by the WNT3a ligand or inhibitor of GSK-3β kinase induced apoptosis in melanoma and neuroblastoma cell lines due to the upregulation of the expression of pro-apoptotic gene BCL2L11 in melanoma, and the downregulation of cyclin D1 in neuroblastoma." (PMID 36612190, 2022). "Therefore, we have chosen MMP2, MMP9, Pyk2, and Cyclin D1 as tumor metastasis indicators to explore the mechanism of how PCDH9 and RAC1 act on melanoma." (PMID 36387162, 2022). "Moreover, miRNA-193b downregulates CCND1 and CCND2 genes, which results in the promotion of melanoma cell proliferation and invasion." (PMID 36224606, 2022). "By analysis of IHC, the median IHC score was 15% (range: 1–80%) in acral melanomas with no CCND1 copy number alteration." (PMID 34225728, 2021). "Comparing FISH and IHC, cyclin D1 protein expression level has no corelation with the CCND1 copy number in acral melanomas which have no CCND1 copy number alteration and low-level CCND1 copy number increase (P = 0.108)." (PMID 34225728, 2021).
melanoma (continued). "The cyclin D1 protein expression level has no corelation with CCND1 copy number in acral melanomas with no CCND1 copy number alteration and low-level copy number increase (P = 0.108)." (PMID 34225728, 2021). "EGFP was used as a negative control, and we tested CCND1 as an additional positive control (known driver often amplified in melanoma [Cancer Genome Atlas Network, 2015])." (PMID 33527896, 2021). "Since HuR knockdown reduced cyclin D1 and cyclin E1 and concomitantly increased the expression of p27, we evaluated the cell cycle profile of melanoma (MeWo and A375) and melanocytes with and without the HuR-NP exposure." (PMID 33418925, 2021). "Additionally, melanoma cell lines and tumor models that are resistant to the BRAF inhibitor vemurafenib exhibit reactivated MAPK signaling and upregulated cyclin D1, and are sensitive to abemaciclib treatment." (PMID 33806615, 2021). "Based on the impact of CCND1 amplification as a negative prognostic factor for efficacy of ICIs in melanoma, we further investigated its role in patients with a solid tumor." (PMID 32903763, 2020). "The expression of CXCL8 and CCND1 was significantly diminished in all melanoma cell lines, irrespective of their basal mRNA and protein levels that confirmed the inhibitory effect of 17-aminogeldanamycin on NF-κB activity." (PMID 32466509, 2020). "Thus, we studied the effect of KYN, KYNA and FICZ on the protein level of cyclin D1, CDK4 and Rb phosphorylation in melanoma A375 and RPMI7951 cells." (PMID 33114713, 2020). "To study whether LEF1 is required to suppress the expression of Wnt/β-catenin target genes, we analyzed c-Myc, Cyclin D1, and Axin-2 mRNA levels in LEF1 knocked-down A375 melanoma cells." (PMID 32933177, 2020). "Although our findings suggest a potential role of cyclin D1 during early invasion of melanoma cells, expression of this protein alone does not appear to be of prognostic significance." (PMID 32374893, 2020). "The reduced expression of lncRNA GAS5 contributed to redox balance and cell cycle progression through increasing expression of Cyclin D1, CDK4, and NOX4, suggesting downregulated GAS5 and increased ROS levels as promising diagnosis or prognosis biomarker for malignant melanoma." (PMID 35006436, 2020). "Although a direct involvement of CCND1 has been identified only in human acral and mucosal melanomas, and not in COMs, high expression of Cyclin D1 protein in COMs has been recently documented." (PMID 31921654, 2019). "Genomic profiling of 23 available subjects also identified gene amplifications of cell cycle regulators (Cyclin D1, CDK4, or CDK6), fibroblast growth factors (FGF19, FGF3, and FGF4) and EMSY (a DNA repair inactivating gene) uniquely clustered in acral melanoma subjects in the study." (PMID 30642373, 2019). "Furthermore, besides SF3B1 and KIT mutations, other variants have been described in the context of mucosal melanoma, including amplifications of CCND1, MDM2 and KRAS, however this was not assessed this cohort and could represent a source of additional driver eventsin this cohort." (PMID 30847022, 2019). "Activation of p38 has a negative effect such as mitotic arrest and cyclin D1 reduction in cell proliferation, while p38 inhibitors inhibited melanoma cell proliferation by HGF in another report." (PMID 30223485, 2018). "Therefore, we can say that RGS4 inhibits Cyclin D1 via PI3k/AKT signaling pathway for proliferation, migration of melanoma cells." (PMID 29108247, 2017). "In addition, treatment of LY294002 on the cells blocked activation of PI3K/AKT, Cyclin D1 and E2F1 due to the knockdown of RGS4 in melanoma cells and consequently decreased the expression of p-Akt, Cyclin D1 and E2F1." (PMID 29108247, 2017).
melanoma (continued). "The only exception was the influence of trametinib on CCND1 expression, as trametinib reduced CCND1 expression in melanoma cells grown in medium without growth factors for at least 10 weeks to significantly higher extent than in melanoma cells grown in SCM." (PMID 28829835, 2017). "Moreover, we show that the suppression of NAT10 reduces melanoma growth with abnormal expression of cell cycle-regulating genes such as CDK2 and cyclin D1 in vitro and in vivo." (PMID 28880216, 2017). "In this study, our results supported the hypothesis that RGS4 led to downregulation of Cyclin D1 and E2F1 expression via inactivation of the GPCR-mediated PI3K/AKT pathway, and as the results, inhibited melanoma cell growth, proliferation and so on." (PMID 29108247, 2017). "Interestingly, wogonin inhibited the mRNA expression of cyclin D1 (CCND1), which regulates G1/S phase cell cycle progression and is upregulated in human melanomas." (PMID 28182699, 2017). "Our results also highlight the importance of the Wnt/β-catenin and their transcriptional targets (including c-myc, survivin, cyclin D1, CDK4, and MMPs), which may serve as future targets for the development of therapeutic strategies against human melanoma." (PMID 26968952, 2016). "Moreover, the suppression of cyclin D1 and cyclin E by CoQ0 led to the inhibition of CDK4 and CDK2 levels in melanoma cells." (PMID 26968952, 2016). "At the molecular level, VS-5584 blocked AKT-mTOR activation and downregulated cyclin D1 expression in melanoma cells, while the expressions of Bcl-xL and Bcl-2 were not affected by VS-5584 treatment." (PMID 26204252, 2015). "Moreover, the level of cyclin D1 protein was proportional to the level of RICTOR in the clones suggesting a role for RICTOR in cyclin D1 expression and melanoma proliferation." (PMID 26356562, 2015). "Indeed, Mep50, cyclin D1 and STAT3 were expressed in melanoma lines, and Mep50 was predominantly cytoplasmic (data not shown)." (PMID 24098663, 2013). "Curtin and colleagues showed that primary melanomas arising from chronically sun-damages skin and mucosal sites, the latter of which typically do not harbor BRAF and NRAS mutations, have increased CCND1 copy number." (PMID 21479172, 2011). "Decreased expression of Cyclin D1 and RB1 proteins has previously been reported in melanoma." (PMID 21615965, 2011). "For instance, our Bio-LDA model suggested that there might be protein protein-protein interactions between CCND1 and EGFR, since both of them are important targets in the tumor related diseases: Carcinoma and Melanoma." (PMID 21448266, 2011). "Unlike primary melanomas, >15% of metastatic melanoma samples with BRAF mutations exhibit amplification of CCND1." (PMID 21479172, 2011). "Finally, treatment of basal pSTAT3-positive human melanoma cell lines with FLLL32 for 24 hours led to reduced STAT3 DNA binding as determined by gel shift assays and expression of the STAT3-regulated genes, cyclin D1 and survivin as measured by immunoblot." (PMID 20576164, 2010). "Similar to the melanoma model, in MSI CRC cells, it was shown that BRAF V600E–ERK signalling is important in the regulation of proliferation through the p27Kip1 and cyclin D1 proteins." (PMID 20485284, 2010). "Furthermore, it was discovered that by concurrently blocking the MAPK/c-Myc/cyclin D1 and STAT3/SOX2 pathways, a combination of DHT and MAPK pathway inhibitors could accelerate the death of melanoma cells." (PMID 39944829, 2025). "Immunohistochemically, the tumor cells were positive for S100 (5/6), cyclin D1 (2/3), SATB2 (2/3), BCOR (2/4), and TLE1 (1/3) while negative for MUC4 (0/6), keratin (0/5), EMA (0/4), desmin (0/6), CD34 (0/6), SMA (0/5), SOX10 (0/5), and melanoma cocktail (0/2)." (PMID 40705064, 2025).
melanoma (continued). "Nuclear expression of PRAME (Preferentially expressed Antigen in Melanoma), cyclin D1 positivity and loss of p16 on immunohistochemistry can also be helpful in distinguishing Co-M from naevi or low-grade C-MIL (both PRAME and cyclin D1 negative, p16 positive)." (PMID 39335093, 2024). "Rivoeranib is a tyrosine kinase inhibitor that selectively inhibits VEGFR2, which can effectively inhibit canine melanoma in vitro and in vivo; it inhibits proliferation and migration, induces cell cycle arrest and apoptosis, and down-regulates VEGFR2 phosphorylation and cyclin-D1 expression." (PMID 39408717, 2024). "Although the alteration of PCDH9 could influence CCND1 but not the cell cycle, which suggested it may affect melanoma cells by other mechanisms, such as SOCE combined melanoma cell migration, RAC1-dependent NADPH oxidase correlated with GTP-GDP switch." (PMID 36452505, 2022). "Considering CCND1 is an important driver of CDK4, CDK4/6 inhibitors as monotherapy or in combination with ICIs may represent a highly promising treatment for patients with melanoma harboring CCND1 amplification." (PMID 35844619, 2022). "This suggests that angiogenesis may not contribute to the initiation and progression of melanoma tumors harboring a CCND1 amplification, and antiangiogenic agents may not be effective in this subset of patients." (PMID 35844619, 2022). "We analyzed CCND1 amplification of 6,536 patients from the Geneplus 1,021 panel in a Chinese population and found that HNSCC had a high CCND1 amplification in 25.00% of the cases (7/28), followed by ESCA in 23.88% (16/67), BLCA in 9.76% (8/82), and melanoma in 6.67% of cases (6/90)." (PMID 32903763, 2020). "Interestingly, the member EIF4E of the family is reported to increase the level of Cyclin D1 protein in vitro, while other members (components of the EIF3 complex, in particular), have been correlated to human cancer, and human melanoma." (PMID 31921654, 2019). "Neither cell distribution in cell cycle and CCND1 expression nor activity of signaling pathways crucial for melanoma development and maintenance, including the RAF/MEK/ERK pathway, WNT/β-catenin pathway and NF-κB signaling, were affected by the presence of different growth factors." (PMID 28829835, 2017). "In this paper, we could also show that, in BLM melanoma cells, ERβ agonists exert their antiproliferative activity through the modulation of cell cycle progressing factors (cyclin D1, cyclin D3, p27), without triggering the apoptosis pathway." (PMID 26225426, 2015). "For example MGHU1 human bladder cancer and G361 human melanoma cells both exhibited total cell death with the same dose of 200 μM THR53 but respectively had markedly different endogenous Cdk4 values of 3.605 ± 0.735 and 6.035 ± 1.765 and Cyclin D1 values of 3.465 ± 0.832 and 1.055 ± 0.292." (PMID 21668989, 2011). "However, CGH analysis of our panel of seven melanoma cell lines did not reveal amplifications in cyclin D1 or CDK4 (data not shown)." (PMID 17245336, 2007). "Therefore, we conclude that ICIs may not be a suitable treatment for patients with melanoma harboring a CCND1 amplification." (PMID 35844619, 2022). "Due to the detection of the V600E BRAF mutation in this fistula melanoma, it was decided not to look for alterations in genes such as CCND1 or KIT, more frequently mutated in acral and mucosal melanomas, since concomitant mutations in BRAF and in genes such as KIT or CCND1 are extremely rare." (PMID 21827678, 2011). "WGS studies have suggested that TWT melanomas, commonly of the AM subtype, are more likely to have focal amplifications of CCND1, MDM2, KIT, and KRAS, as well as CDK4 and CDK6, than non-TWT melanomas." (PMID 39858514, 2025). "PCDH9 and CCND1 (Cyclin D1) exhibited a positive correlation, whereas MMP2, MMP9, and RAC1 exhibited a negative correlation with both melanoma A375 and G361 cells." (PMID 36452505, 2022).
melanoma (continued). "Our studies revealed that KYN inhibited the protein level of cyclin D1 and CDK4 in melanoma A375 cells, but not in more resistant RPMI7951 cells." (PMID 33114713, 2020). "The influence of drugs on the expression of CCND1, CXCL8 and CTGF was also similar, when impact of drugs on the gene expression was compared between melanoma cells grown in SCM and the medium without growth factors for 2 days, 10 weeks and 3–4 months." (PMID 28829835, 2017). "Curiously, cyclin D1 protein expression was negative in all nevi and markedly expressed in RGP melanomas and metastases, and significantly downregulated in VGP melanomas." (PMID 22110486, 2012). "Interestingly, we did not observe significant changes in the protein level of cyclin D1 and CDK4 in melanoma A375 and RPMI7951 cells exposed to FICZ." (PMID 33114713, 2020). "In SK-MEL-28 melanoma cell lysates, ABT888 drug exhibited an anti-proliferative action by the inhibition of AKT as demonstrated by decreased levels of pAKT, while the levels of Cyclin D1 and c-Myc were not affected." (PMID 27461275, 2016). "Ultimately the lack of interaction between PRMT5 and cyclin D1 or STAT3, and differences in subcellular localization, suggest that the role of PRMT5 in melanoma may differ from its role in other cancers." (PMID 24098663, 2013). "Amplification of the other two genes may not be important in the tumorigenesis of melanomas, as only one CDK4 and no CCND1 amplification was observed." (PMID 8611425, 1996). "However the sensitivity of CCND1 FISH for evaluation of acral melanocytic tumors is not high, and this relatively low sensitivity may result from the high heterogeneity of melanoma." (PMID 34225728, 2021).